KRAS (KRas proto-oncogene, GTPase)
Diseases named in the same sentence as KRAS in open-access papers (continued):
Sharing a sentence is not in itself a finding about the gene and the disease.
rectal tumors (44 papers, 2005 to 2025). "KRAS p.Gly12Cys (G12C) mutation was frequent in rectal tumors (52.4%), while p.Gly13Asp (G13D) mutation predominated in right-sided tumors (45.3%)." (PMID 39857025, 2025). "Rectal tumors exhibit distinctive biological characteristics when compared to left-sided tumors, including a higher absence rate of KRAS, NRAS, and BRAF mutations (47.4% in rectal versus 42.8% in left-sided tumors)." (PMID 38409377, 2024). "In our patient cohort, we found that KRAS exon 4 mutations were significantly associated with rectal tumor localization." (PMID 37628934, 2023). "Our most significant finding was the higher prevalence of exon 4 KRAS mutations in rectal tumors compared to tumors in other colon segments (OR = 3.23, 95% CI: 1.19–8.72, p = 0.021)." (PMID 37628934, 2023). "The rectal tumors displayed a higher ratio of KRAS G12 mutations (G12D 34%, G12V 27%, G12A 9%, G12C 3%) compared to the tumors from the colon." (PMID 36439454, 2022). "KRAS and BRAF wild-type cases were slightly younger at diagnosis and more often had rectal tumors compared to the KRAS-mutated cases." (PMID 32210264, 2020). "This is in keeping with previously published data that suggested an association between both rectal tumours and KRAS mutations and the development of PM, although the KRAS mutation rates previously reported range from 36–62% for PM samples." (PMID 29029407, 2017). "KRAS mutations identified in locally advanced or local recurrent rectal tumors and lavage formerly labeled to be an independent poor prognostic factor on overall survival was not validated." (PMID 28592327, 2017). "Initially these patients were included in a pilot study where KRAS mutations in exon 1 identified in primary rectal tumors and lavage was reported to be an independent poor prognostic factor for overall survival." (PMID 28592327, 2017). "A trend for decreased incidence of KRAS mutations in rectal tumors was observed (p = 0.097) since 31 of the 83 (37%) tumours located at the colon and six of the 29 (20%) tumours located at the rectum harbored a KRAS mutation." (PMID 21283802, 2011). "Most KRAS codon 61 mutations occurred in rectal tumors (47.1%)." (PMID 39857025, 2025). "Therefore, it was not surprising to find that dietary fiber was significantly associated with reduced risk of rectal tumors overall as well as with reduced risk of KRAS tumor mutations." (PMID 32723394, 2020). "Additionally, a recent study conducted a transcriptomic analysis and revealed that KRAS-mutated rectal tumour cells could remodel the extracellular matrix around their surrounding fibroblasts." (PMID 38087207, 2023). "Additionally, KRAS exon 3-mutated CC tended to be correlated with the rectal tumor site." (PMID 33784337, 2021). "We previously reported that intratumoral injection of OBP-301 suppresses lymph node metastasis in an orthotopic rectal tumor model with KRAS-mutant HCT116 cells." (PMID 37972012, 2023). "A tendency was found in the Japanese population where mutations in KRAS or NRAS were more common in rectal tumors, while our analysis showed a tendency in the proximal colon for KRAS-mutated and rectal tumors for NRAS-mutated." (PMID 32628708, 2020). "Among studies that separated rectal tumors from left‐sided tumors, the summary prevalence of RAS, KRAS, and BRAF mutations among rectal tumors was 34.3%, 30.8%, and 8.8%, respectively." (PMID 31856410, 2020). "Primary rectal tumor tended to be more frequently observed in KRAS exon 2 and other RAS mutant tumors than in RAS wild-type tumors (60.0 vs. 61.9 vs. 48.3%, P = 0.08), although this was not statistically significant." (PMID 25886136, 2015). "Pathologic CR was obtained in 1 KRAS wild-type patient (33%), with primary rectal tumor and a single L-L metastasis." (PMID 24715238, 2014).
rectal tumors (continued). "Hutchins reported that KRAS mutant tumors were more evenly distributed: 40% right colon, 28% left colon, and 36% rectal tumors compared to BRAF mutant tumors." (PMID 22206623, 2011). "When biopsy is not possible, KRAS mutations in rectal tumors have been linked to extended axial dimensions and changed shape metrics on pretreatment imaging, guiding appropriate treatment options." (PMID 40506947, 2025). "SDR16C5 has been found to be upregulated in KRAS-mutant rectal tumors compared to KRAS wild-type, and increased SIRPA may be indirectly linked to mutant KRAS through the overexpression of the EZH2 polycomb complex." (PMID 37141389, 2023). "When an alternate definition of PTL was used (patients with rectal tumors were not included in the LS group), a similarly significant interaction between tumor side and KRAS mutational status was observed." (PMID 35159066, 2022). "Mucinous rectal tumors are more likely to be MSI-H, BRAF mutated and KRAS mutated which could potentially result in an impaired response to cytotoxic chemotherapy and EGFR inhibitors although this is only a hypothesis and needs to be confirmed prospectively with a much larger cohort." (PMID 32984045, 2020). "KRAS/BRAF wild-type cases were characterized by a lower age at diagnosis and a higher proportion of rectal tumors." (PMID 29694444, 2018). "Furthermore, our PCA performed with the TCGA cohort, based on expression data from different gene sets (all deregulated genes or subsets of genes from the Qiagen PCR Arrays) did not allow discriminating colon vs. rectal tumors or CRC samples according to APC or KRAS mutational status." (PMID 28962550, 2017). "Primary rectal tumor tends to be more frequently observed in KRAS exon 2 and other RAS mutant tumors rather than RAS wild-type tumors, although this was not statistically significant." (PMID 25886136, 2015). "The variable effect of KRAS status on PTL persisted regardless of whether patients with rectal tumors were included in the LS group." (PMID 35159066, 2022). "Furthermore, a meta-analysis published in 2022 revealed that the variable effect of KRAS status on PTL persisted, regardless of whether the patients with rectal tumors were included or not in the LS group." (PMID 36013567, 2022).
Obesity (40 papers, 2014 to 2026). Accumulation of substantial excess body fat. "This review is intended to provide an update on our knowledge of the vulnerability of the pancreas to KRAS-mediated invasive PDAC in the context of challenges engendered by obesity and associated inflammation." (PMID 33668583, 2021). "These include KRAS mutations in addition to many others, metabolic and environmental stressors, and obesity." (PMID 34638560, 2021). "Changes in the TME, including gut microbiota, inflammation, intestinal peptides, and insulin resistance, which are associated with obesity, can enhance the activation of KRAS." (PMID 34638560, 2021). "High expression of Fat mass-and obesity-associated gene (FTO) was associated with KRAS signaling up." (PMID 32903217, 2020). "We demonstrated most mutation type of PIK3AC and KRAS was missense mutation in both normal and obesity groups." (PMID 33197880, 2020). "A deeper understanding of the mechanistic role of mutant KRAS and physiological and biochemical changes precipitated by obesity, diets high in fat, and the associated inflammatory microenvironment is needed to develop novel and effective preventive and therapeutic strategies for PDAC." (PMID 33668583, 2021). "In this regard, obesity and inflammation are considered among the most predominant clinical risk factors and are likely to synergize with mutant KRAS to drive pancreatic tumorigenesis leading to invasive PDAC, in which oncogenic KRAS is known to be hyperactivated." (PMID 33668583, 2021). "In addition, we also show that the combined effects of KRAS mutation in the pancreas and obesity are associated with the greater loss of NK cell cytotoxic function." (PMID 29977235, 2018). "We envisage CREB as a key node in a signaling network engaged by stress and obesity that promotes the progression of KRAS-initiated pancreatic cells." (PMID 41484057, 2026). "Obesity induces ectopic expression of cholecystokinin in pancreatic β-cells, which can independently drive KRAS-mediated tumorigenesis." (PMID 40732935, 2025). "Observing the expected role of KRAS variation as well as worse survival of older patients, those diagnosed at late stage, and those who had prediagnosis obesity suggest the validity of our findings." (PMID 36239938, 2022). "Taken together, FGF21 functions, at least in part, to offset the vulnerability that is incurred by oncogenic KRAS and hijacked by obesity and other inflammatory states." (PMID 33668583, 2021). "Recently, the discovery of fibroblast growth factor 21 (FGF21) as a novel anti-obesity and anti-inflammatory factor and as a downstream target of mutant KRAS has shed new light on this problem." (PMID 33668583, 2021). "Experimentally, chronic consumption of a HFD is often used to induce obesity, diabetes, fatty tissue diseases, and meta-inflammation in several tissues, and to promote both chemically-induced and oncogenic KRAS-mediated pancreatic carcinogenesis." (PMID 33668583, 2021). "The recent discovery of FGF21 as an anti-obesity and anti-inflammation factor and as a downstream target of KRAS has shed new light on the problem." (PMID 33668583, 2021). "In summary, we demonstrated the gene mutation frequency (especial in PIK3CA and KRAS), as well as CNV of obesity groups, were decreased." (PMID 33197880, 2020). "We also found that fibroblast growth factor 3 (FGF3), upstream of KRAS, is associated with a hypomethylated DMR in its promoter region in obesity and is even further hypomethylated in CRC." (PMID 30911103, 2019). "Moreover, accumulation of DNA mutations, such as APC, KRAS, NRAS, BRAF, or PIK3CA, makes obesity a multifactor phenomenon involved in CRC initiation and progression." (PMID 36235624, 2022).
Obesity (continued). "This makes KRAS a potential drug target to regulate obesity." (PMID 34948427, 2021). "A possible explanation for this observation could be several signals triggered by high insulin levels and obesity that promote proliferation, especially through the KRAS pathway." (PMID 33228173, 2020). "Interestingly, more co-occurrences between mutations were demonstrated in obesity group compared with normal group (APC and KRAS, PIK3CA and KRAS, etc.)Finally, we investigated the copy number variation (CNV) in two group." (PMID 33197880, 2020). "The frequency of KRAS and PIK3CA mutations were significantly decreased in obesity group." (PMID 33197880, 2020). "Moreover, accumulation of DNA mutations, as in APC, KRAS, NRAS, BRAF, or PIK3CA, and insulin secretion sets obesity as a multifactor phenomenon involved in CRC initiation and aggressive development." (PMID 26801617, 2016). "Since KRAS and BRAF mutations are thought to occur early in colorectal carcinogenesis, it seems biologically plausible that exposures such as obesity might modulate CRC risk differentially according to KRAS and BRAF mutation status of the tumours." (PMID 24918610, 2014). "In this prospective cohort study, we have investigated the relationship between obesity, measured as several anthropometric factors, and risk of CRC according to KRAS and BRAF mutation status of the tumours, with particular reference to potential sex differences." (PMID 24918610, 2014). "By further analyzing these overlapping DMRs, we observed DNA methylation changes in extracellular matrix components and organization, O-glycan processing, and intracellular factors including KRAS signaling and lipid and glucose metabolism, all pathways that may enhance the CRC risk in obesity." (PMID 30911103, 2019). "KRAS signaling is also a shared component in signaling pathways regulating pluripotency of stem cells, microRNAs in cancer and oxytocin signaling pathway (hsa04550, hsa05206, and hsa04921, respectively), suggesting its central role in obesity and cancer pathology." (PMID 30911103, 2019). "Hence, the aim of this prospective cohort study was to investigate the associations of obesity, measured as several anthropometric factors, with CRC risk according to KRAS and BRAF mutation status of the tumours, overall, and with particular reference to potential sex differences." (PMID 24918610, 2014). "Although the mechanisms by which obesity promotes PDAC are complex, obesity mediators stimulate the function of two key molecular mediators of PDAC, namely, KRAS and YAP." (PMID 41484057, 2026). "Existing experimental testimony shows highly penetrant PC with a mutant KRAS gene, a critical oncogene in the initiation, proliferation and metabolic reprogramming of PDAC, develops fast when faced with food-induced obesity and inflammation." (PMID 35875143, 2022). "In this review, we will focus on the interplay of obesity (e.g., adipose tissue dysfunction and meta-inflammation), oncogenic KRAS, and metabolic and inflammatory regulators, in particular FGF21, a novel anti-obesity and anti-inflammation factor, in the development of PDAC." (PMID 33668583, 2021). "The intron region of KRAS was hypermethylated in both CRC and obesity." (PMID 30911103, 2019). "The signal-transduction pathways dysregulated by DNA methylation changes in both obesity and CRC include: 1) extracellular matrix components, i.e., O-glycan processing, protein glycosylation, and extracellular matrix scaffold; 2) KRAS and TGF-β signaling; and 3) lipid and glucose metabolism." (PMID 30911103, 2019).
Obesity (continued). "Similar to KRAS and CDKN2A, HFD-induced obesity did not influence methylation levels in these 14 CpGs." (PMID 38622664, 2024).
colorectal adenoma (38 papers, 1996 to 2025). An adenoma that arises from the colon or rectum. "Genetic mutations in the tumor suppressor gene APC and the oncogene KRAS are an initial event in the colorectal adenoma-carcinoma sequence." (PMID 41488735, 2025). "KRAS/NRAS mutations in colorectal adenomas are the only occurrence where we cannot find discriminable protein profiles between cases that would be treated and those which would not." (PMID 30442178, 2018). "Accordingly, most of colorectal adenomas analyzed herein exhibited KRAS (G12D, G13D, Q61H) or BRAF (V600E) activating mutations, in combination with APC inactivating mutations (exon 15)." (PMID 27582544, 2016). "Though coexistence of mutations occurring in BRAF or KRAS has been assumed to be mutually elusive, such phenomena were recently observed in colorectal adenoma/cancer and ovarian malignancies." (PMID 24139521, 2013). "KRAS mutations are considered as an early event in the sequential accumulation of molecular alterations underlying the progression from colorectal adenoma to malignant carcinoma, resulting in an important tumour growth advantage." (PMID 22931052, 2012). "KRAS is one of the most explored genes frequently mutated in colorectal neoplasia; its mutation frequency varies from 20% to 70% in colorectal adenomas, and approx. 40–52% of CRC cases bear KRAS mutation." (PMID 36765865, 2023). "We performed pooled BaseScope staining on 21 colorectal adenomas containing foci of cancer (‘Ca-in-ad’ tumors) which all appeared KRAS wild-type by Sanger sequencing from ‘bulk’ DNA." (PMID 29222441, 2017). "APC and KRAS are observed in colorectal adenoma and carcinoma with the rate of 40–80% and they play a role in early steps of carcinogenesis." (PMID 25945089, 2015). "In addition, activation of mutations in the KRAS (or RAS) oncogene occur at a similar frequency in both SBA and colorectal adenoma tumors, which suggests a potential role for EGFR inhibition in a subset of patients with SBA." (PMID 28536826, 2017). "Finally, we show that E2F4 is overexpressed, phosphorylated and localized in the nucleus of epithelial cells from colorectal adenomas exhibiting APC and KRAS or BRAF mutations." (PMID 23919615, 2013). "Finally, E2F4 was found to be overexpressed, phosphorylated and nuclear localized in epithelial cells from human colorectal adenomas exhibiting mutations in APC and KRAS or BRAF genes, known to deregulate GSK3/β-catenin and MEK/ERK signaling, respectively." (PMID 23919615, 2013). "For KRAS, eight out of the nine nucleotide positions tested showed sufficient results (codon 12: c.34G>CAT, c.35G>ATC, codon 13: c.38G>ACT, c.39C>AGT, codon 59: c.175G>A, codon 61: c.181C>AG, c.182A>TGC, c.183A>CT) covering 98.85% of the mutations described in colorectal adenomas." (PMID 22848674, 2012). "Furthermore, KRAS and BRAF are likely involved in the malignant transformation of colorectal adenomas as driver genes." (PMID 26910894, 2016). "In fact, Paneth cell metaplasia is not only observed in colorectal adenomas but also in the non-neoplastic mucosa surrounding the adenomatous lesion often carrying early genetic alterations (e.g. KRAS)." (PMID 22745693, 2012).